FOLH1B (folate hydrolase 1B (pseudogene))
Description:
Has both folate hydrolase and N-acetylated-alpha-linked-acidic dipeptidase (NAALADase) activity. Exhibits a dipeptidyl-peptidase IV type activity.
Synonyms: PSMAL; formerly FOLH2; FOLHP
Gene: Transcribed unprocessed pseudogene on chromosome 11 (89,639,237 to 89,698,599, forward strand). Ensembl gene ENSG00000134612.
Subcellular location: Cytoplasm
Diseases named in the same sentence as FOLH1B in open-access papers:
FOLH1B is named in the same sentence as 4 diseases in open-access papers, as found by Europe PMC text mining. Sharing a sentence is not in itself a finding about the gene and the disease. The quoted sentences say what the papers report.
prostate carcinoma (3 papers, 2019 to 2021). A carcinoma that arises from epithelial cells of the prostate gland. "Studies suggest FOLH1B may play an important role in the development and progression of prostate cancer." (PMID 34375949, 2021).
psychiatric disorder (1 paper, 2023). A disorder characterized by behavioral and/or psychological abnormalities, often accompanied by physical symptoms. "The gene with the most interactions was, with pAUDIT using PFC expression, FOLH1B, an untranslated pseudogene previously associated with psychiatric disorders and BMI." (PMID 37216417, 2023).
tumor (1 paper, 2020). "Consistently, all the six DEGs (GLS2, ASS1, FOLH1B, AGXT2, CPS1, and GPT2) enriched in “arginine biosynthesis” in our results were significantly downregulated in tumor hepatic tissue from HBV-infected patients compared with adjacent nontumor tissues." (PMID 32775402, 2020).
FOLH1B also shares sentences with these, for which no sentence is quoted: hearing loss (1 paper).